ZNF76 (zinc finger protein 76)
Description:
Transcription factor that regulates expression of genes transcribed by both RNA polymerases II and III. Specifically recognizes and binds the Staf-binding site (SBS), a consensus DNA-binding motif present in many promoters. Able to activate expression of small nuclear RNA (snRNA) transcribed by RNA polymerases II and III. Also regulates expression of mRNAs and acts as a DNA-binding transcription repressor that inhibits the activity of the TATA-binding protein (TBP).
Synonyms: D6S229E; ZNF523; Zfp523
Tractability: PROTAC: UniProt records ubiquitination sites on it; ubiquitination databases record sites on it.
Gene: Protein-coding gene on chromosome 6 (35,258,909 to 35,295,985, forward strand). Ensembl gene ENSG00000065029.
Subcellular location: Nucleus; Chromosome
Subcellular location (Human Protein Atlas): Nucleoplasm; Cytosol
Gene Ontology:
Molecular function: DNA-binding transcription activator activity, RNA polymerase II-specific; DNA-binding transcription repressor activity, RNA polymerase II-specific; protein binding; sequence-specific DNA binding; sequence-specific double-stranded DNA binding; DNA-binding transcription factor activity, RNA polymerase II-specific; RNA polymerase II cis-regulatory region sequence-specific DNA binding
Biological process: negative regulation of transcription by RNA polymerase II; positive regulation of transcription by RNA polymerase II; regulation of transcription by RNA polymerase II; regulation of transcription by RNA polymerase III
Cellular component: chromatin; chromosome; nucleus
Genetic constraint (gnomAD): Loss-of-function variants: 65 observed, 66.76 expected, observed/expected ratio (o/e) 0.97, 90% interval 0.8 to 1.2. The upper end of that interval is the gene's LOEUF score, 1.2, which puts it in group 5 of 6, group 1 being the genes least tolerant of losing a copy. Missense variants: 721 observed, 792.18 expected, observed/expected ratio (o/e) 0.91, 90% interval 0.86 to 0.97. Synonymous variants: 271 observed, 309.34 expected, observed/expected ratio (o/e) 0.88, 90% interval 0.79 to 0.97.
Homologues: Orthologues: chimpanzee ZNF76 (99% identical), macaque ZNF76 (98% identical), pig ZNF76 (96% identical), rabbit ZNF76 (96% identical), dog ZNF76 (95% identical), mouse Zfp523 (92% identical), guinea pig ZNF76 (92% identical), rat Zfp523 (81% identical), zebrafish znf76 (58% identical). Paralogues in human: ZNF143 (58% identical), MTF1 (21% identical), PATZ1 (18% identical), PRDM10 (18% identical), ZNF281 (17% identical), ZNF148 (17% identical), ZBTB16 (16% identical), PRDM1 (16% identical), VEZF1 (16% identical), ZNF384 (15% identical), ZNF362 (15% identical), ZNF410 (15% identical), and 24 more.
Diseases named in the same sentence as ZNF76 in open-access papers:
ZNF76 is named in the same sentence as 11 diseases in open-access papers, as found by Europe PMC text mining. Sharing a sentence is not in itself a finding about the gene and the disease. The quoted sentences say what the papers report.
breast cancer (2 papers, 2014 to 2021). A primary or metastatic malignant neoplasm involving the breast. "Compared with a high expression level, a low expression level of ZNF76 was also correlated with a poorer prognosis in breast cancer and lung cancer." (PMID 34793589, 2021). "Notably, the low expression of ZNF76 was also found strongly correlated to poor survival in colorectal cancer, brain cancer, breast cancer, and lung cancer." (PMID 34793589, 2021).
autoimmune disease (1 paper, 2021). A disorder resulting from loss of function or tissue destruction of an organ or multiple organs, arising from humoral or cellular immune responses of the individual to their own tissue constituents. "Considering both genetic clues concerning variants in zinc finger protein-coding genes contributing to susceptibility to autoimmune diseases, including SLE, and the biological functions of ZNF76, we aimed to explore the role of ZNF76 in the pathogenesis of SLE." (PMID 33664275, 2021).
leukemia (1 paper, 2021). A malignant (clonal) hematologic disorder, involving hematopoietic stem cells and characterized by the presence of primitive or atypical myeloid or lymphoid cells in the bone marrow and the blood. "Compared to healthy BMMCs, we observed the TF networks of ZNF266, RORA, GTF3C2, ZNF76, ZNF383, IRF5 and NFE2L2 being top upregulated in all leukemia patients." (PMID 33408321, 2021).
cancer (1 paper, 2021). A tumor composed of atypical neoplastic, often pleomorphic cells that invade other tissues. "However, few pertinent studies associated with ZNF76 in cancers have been reported." (PMID 34793589, 2021). "The impact of ZNF76 expression on survival rates of pan-cancer was evaluated using the PrognoScan." (PMID 34793589, 2021). "Moreover, the prognosis value of ZNF76 was validated in pan-cancers through the bioinformatics analysis from public data." (PMID 34793589, 2021). "Furthermore, we visualized the prognostic landscape of ZNF76 in pan-cancer using databases, including PrognoScan, GEPIA 2, and Kaplan–Meier Plotter." (PMID 34793589, 2021). "Moreover, the prognosis value of ZNF76 in pan-cancer was validated from multiple cohorts." (PMID 34793589, 2021). "In addition, we visualized the prognostic landscape of ZNF76 in pan-cancer using databases." (PMID 34793589, 2021).
neoplasm (1 paper, 2021). A benign or malignant tissue growth resulting from uncontrolled cell proliferation. "Studies have shown ZNF76 is associated with a range of phenotypic abnormalities that affect embryonic development, male fertility, and neoplasia." (PMID 34793589, 2021). "The results showed that ZNF76 mRNA levels were significantly associated with OS when age, stage, grade, and tumor residual size were included in the model (P=0.018, HR = 0.7, 95%CI = 0.51–0.94)." (PMID 34793589, 2021). "RT-qPCR and IHC assay shown that the ZNF76 mRNA and protein expression were significantly lower in OV tumor than that in normal ovary tissues." (PMID 34793589, 2021). "The results suggested ZNF76 may act as tumor suppressor in OV." (PMID 34793589, 2021). "Although some members of the ZnF proteins were demonstrated to be carcinogenic in many neoplasms, the gene expression profile and prognostic value of ZNF76 in OV were still not elucidated." (PMID 34793589, 2021). "In the present study, we found that ZNF76 was decreased expressed in OV tumor tissue compared with normal ovary tissues." (PMID 34793589, 2021). "In the present study, our results confirmed that the expression of ZNF76 was significantly lower in OV tumor compared to that in normal ovary tissues." (PMID 34793589, 2021).
ZNF76 also shares sentences with these, for which no sentence is quoted: brain cancer (1 paper); colorectal cancer (1); invasive breast carcinoma (1); lung carcinoma (1); ovarian carcinoma (1); systemic lupus erythematosus (1).